IL17RB (interleukin 17 receptor B)
Description:
Receptor for the pro-inflammatory cytokines IL17B and IL17E. May play a role in controlling the growth and/or differentiation of hematopoietic cells.
Synonyms: IL17Rh1; CRL4; EVI27; IL17BR
Tractability: Antibody: its Gene Ontology location is reachable by antibodies, with high confidence; UniProt places it where antibodies can reach, with medium confidence; UniProt predicts a signal peptide or a membrane-spanning region.
Gene: Protein-coding gene on chromosome 3 (53,845,783 to 53,866,045, forward strand). Ensembl gene ENSG00000056736.
Subcellular location: Cell membrane (Isoform 1); Secreted (Isoform 2)
Subcellular location (Human Protein Atlas): Plasma membrane; Vesicles
Pathways (Reactome):
Immune System: Interleukin-17 signaling
Gene Ontology:
Molecular function: protein binding; cytokine receptor activity; interleukin-17 receptor activity
Biological process: defense response; interleukin-17-mediated signaling pathway; positive regulation of cytokine production involved in inflammatory response; positive regulation of interleukin-13 production; positive regulation of interleukin-5 production; protein K63-linked ubiquitination; regulation of cell growth; regulation of keratinocyte proliferation; T-helper 17 type immune response
Cellular component: plasma membrane; membrane; cell surface; cytoplasm; extracellular region
Genetic constraint (gnomAD): Loss-of-function variants: 26 observed, 32.19 expected, observed/expected ratio (o/e) 0.81, 90% interval 0.59 to 1.12. The upper end of that interval is the gene's LOEUF score, 1.12, which puts it in group 4 of 6, group 1 being the genes least tolerant of losing a copy. Missense variants: 552 observed, 581.66 expected, observed/expected ratio (o/e) 0.95, 90% interval 0.88 to 1.02. Synonymous variants: 212 observed, 217.75 expected, observed/expected ratio (o/e) 0.97, 90% interval 0.87 to 1.09.
Homologues: Orthologues: chimpanzee IL17RB (98% identical), macaque IL17RB (96% identical), pig IL17RB (81% identical), guinea pig IL17RB (76% identical), dog IL17RB (75% identical), mouse Il17rb (75% identical), rat Il17rb (74% identical), rabbit IL17RB (71% identical), tropical clawed frog il17ra (23% identical), zebrafish il17ra1a (21% identical), zebrafish il17ra1b (20% identical), Caenorhabditis elegans ilcr-1 (15% identical), and 1 more. Paralogues in human: IL17RA (24% identical), IL17RD (17% identical), IL17RE (15% identical), IL17RC (13% identical).
Diseases named in the same sentence as IL17RB in open-access papers:
IL17RB is named in the same sentence as 103 diseases in open-access papers, as found by Europe PMC text mining. Sharing a sentence is not in itself a finding about the gene and the disease. The quoted sentences say what the papers report.
breast cancer (51 papers, 2010 to 2025). A primary or metastatic malignant neoplasm involving the breast. "High expression of IL‐17B and IL‐17RB has been associated with poor prognosis in different cancer types, including breast cancer, glioblastoma, lung cancer, gastric cancer, and colon cancer." (PMID 36325957, 2023). "Meanwhile, the high expression of the IL-17B/IL-17RB axis has been associated with poor prognosis of several cancers, including breast cancer, lung cancer, and gastric cancer." (PMID 37686343, 2023). "In breast cancer, high expression of IL17RB is associated with poor prognosis that is mainly the result of the interaction between IL-17B and IL17RB." (PMID 36267311, 2022). "Our findings indicate that IL‐17RB can be used as a new diagnostic marker for LN biopsy and a potential target for inhibition of distant organ metastasis in breast cancer." (PMID 28993429, 2017). "Here we found that high expression of IL-17B and IL-17RB is associated with poor prognosis in patients with breast cancer and that IL-17B expression upregulation is specifically associated with poorer survival in patients with basal-like breast cancer." (PMID 29371916, 2017). "Indeed, unlike IL-17B, IL-17E (or IL-25) causes caspase-mediated apoptosis of breast cancer cells and reduces colony formation of IL17RB-expressing breast tumor cell lines in vitro." (PMID 32373132, 2020). "The results showed that IL17RB expression was increased in breast cancer cell lines overexpressing CHDH." (PMID 40928004, 2025). "Overexpression of membrane receptors is a common characteristic in different cancer types, such as ER and IL17RB in breast cancer." (PMID 40928004, 2025). "Recent studies showed that the IL17B/IL17RB cascade promotes antiapoptosis and tumorigenesis in breast cancer and facilitates invasion, vasculogenic endothelial cells and the macrophage recruitment of pancreatic cancer cells." (PMID 39590310, 2024). "In a recent study, breast cancer patients with high levels of IL-17RB had a higher correlation with poor prognosis compared to patients with high levels of HER2." (PMID 37686343, 2023). "The study also suggests that IL-17RB promotes the progression of breast cancer through the NF-κB pathway." (PMID 37686343, 2023). "Studies have revealed that IL-17E inhibits the formation of breast cancer cell colonies expressing IL17RB in vitro." (PMID 36267311, 2022). "The IL17RB signaling pathway plays a key role in its progression, so targeting this pathway is a potential therapeutic pathway for breast cancer inhibition." (PMID 35205681, 2022). "Recently, another study shows that high expression of IL17B and its receptor IL17RB relates to poor prognosis of breast cancer patients." (PMID 35373393, 2022). "In MCF-7, MDA-MB-157, MDA-MB-361, and MDA-MB-468 human breast cancer cell lines, high levels of IL-17RB as well as high IL-17RB mRNA expression have been observed." (PMID 35954312, 2022). "TGF-β1 released by Tregs in lymph nodes contributes to the upregulation of IL-17RB expression to promote breast cancer malignancy." (PMID 33649532, 2021). "IL-17E, which is also produced by mammary epithelial cells, has been shown to engage the IL-17RB on human mammary cancer cells, and to induce their caspase-dependent apoptosis." (PMID 33244315, 2020). "In mammals, IL-17B is highly expressed in chondrocytes, intestinal epithelial cells, neurons, and breast cancer cells, and IL-17 receptor B (IL-17RB) is expressed by mucosal epithelial cells." (PMID 32517220, 2020). "Other reports show that IL17RB is normally expressed in decidual stroma cells and plays a role in breast cancer." (PMID 30680064, 2018). "Altogether our results emphasize the role of the IL-17B/IL-17RB signaling pathway in breast tumors and identify IL-17B and its receptor as attractive therapeutic targets for potentiating breast cancer chemotherapy." (PMID 29371916, 2017).
breast cancer (continued). "Our findings suggest that TGF‐β1 secreted by Tregs in the TDLNs plays a major role in up‐regulating Il‐17rb in breast cancer cells." (PMID 28993429, 2017). "We thus evaluated the expression of IL-17B and IL-17RB by real-time quantitative PCR in biopsies from a cohort of patients with breast cancer (n = 143) and 10 years of follow-up." (PMID 29371916, 2017). "Previously, we reported that the expression of IL‐17RB was correlated with poor prognosis in breast cancer patients." (PMID 28993429, 2017). "Taken together, these results suggest that Tregs in the TDLNs are the major cell type to induce Il‐17rb expression in breast cancer cells to enhance malignancy." (PMID 28993429, 2017). "The observation that IL-17B effects were not limited to basal-like breast cancer cell lines suggests that the IL-17B/IL-17RB role in TN/basal-like breast tumors is mainly due to upregulation of this pathway rather than to TN/basal-like-specific mechanisms." (PMID 29371916, 2017). "Instead, our results indicated that Tregs in TDLNs directly induced Il‐17rb up‐regulation of breast cancer cells." (PMID 28993429, 2017). "Depletion of Tregs abolished both Il‐17rb induction and aggressive phenotypes in breast cancer cells." (PMID 28993429, 2017). "Wen-Hwa and co-workers first reported that amplified IL-17B/IL-17RB signaling promotes breast cancer tumorigenicity by activating nuclear factor-kB, to upregulate the antiapoptotic factor Bcl-214." (PMID 27146881, 2016). "Consistently with this idea, previous studies have shown that the IL-17RB/IL-17B signaling pathway promotes tumorigenicity and etoposide resistance in breast cancer cells through NFκB activation and Bcl-2 up-regulation." (PMID 27462789, 2016). "The ability of TOX3 to upregulate a number of genes implicated in breast cancer or mammary gland development, including TBX3, BMP7, and IL17RB, was confirmed by qRT-PCR in transiently transfected cells under estrogen-depleted conditions." (PMID 25632947, 2015). "Treatment with blocking IL-17RB therapeutic antibodies attenuated the tumorigenicity of breast cancer cells." (PMID 25340344, 2014). "In the serum of breast cancer patients, IL17RB can be detected by standard ELISA assays." (PMID 40928004, 2025). "Moreover, IL-17RB and IL-17B amplification can promote tumorigenicity in breast cancer via the activation of NF-kB and Bcl-2." (PMID 35954312, 2022). "Interestingly, analysis of IL-17RB expression in lymph node metastasis and matched tumors of breast cancer patients confirmed that IL-17RB is increased in lymph nodes and correlates with FOXP3 frequency." (PMID 34632244, 2021). "Ligation of IL‐25 to its receptor, IL‐17RB, on breast cancer cells also induces apoptosis." (PMID 34128588, 2021). "Nonetheless, targeting the IL-17RB in cancer should be carefully investigated in breast cancer, because it could interfere with the anti-tumor activity of IL-17E." (PMID 33244315, 2020). "Similarly, IL-17B or IL-17RB silencing in cancer cells or treatment with antibodies targeting IL-17RB reduced proliferation of MDA-MB361 breast cancer cells and MOLM-13 AML cells in vitro and tumor growth in vivo in xenograft models based on these cell lines." (PMID 32373132, 2020). "Although these data must be confirmed in a larger cohort of patients, they indicate that in addition to IL-17RB, IL-17B expression level also could influence breast cancer prognosis." (PMID 29371916, 2017). "Importantly, clinical data showed that the expression of IL‐17RB in human breast cancer cells in LNs was positively correlated with the prevalence of Tregs." (PMID 28993429, 2017). "Although high IL-17RB expression was previously associated with poor prognosis in patients with breast cancer, the prognostic value of IL-17B per se has never been investigated." (PMID 29371916, 2017).
breast cancer (continued). "Finally, our results emphasize the role of the IL-17B/IL-17RB signaling pathway in breast cancer and identify IL-17B and its receptor as attractive therapeutic targets for therapy." (PMID 29371916, 2017). "Furthermore, since IL‐17B/IL‐17RB signaling activates NF‐κB in human breast cancer, NF‐κB nuclear translocation can serve as the measurement for the consequence of Il‐17rb induction." (PMID 28993429, 2017). "Thus, various human breast cancer cell lines, in which IL-17RB expression was confirmed by flow cytometry, were cultured in the presence of 10 ng/mL of recombinant human IL-17B (rIL-17B) for 72 h and then incubated with paclitaxel at different concentrations." (PMID 29371916, 2017). "Additionally, it has been suggested that only a minority population of breast cancer patients showed IL-17RB expression in the tumor cells." (PMID 27909985, 2017). "However, whether TGF‐β1 is the solely factor to induce Il‐17rb in breast cancer cells in the TDLNs needs further investigation since other factors such as TNF‐α can also up‐regulate IL‐17RB in primary fibroblast." (PMID 28993429, 2017). "To further investigate whether the Tregs mediated Il‐17rb up‐regulation in the 4T1 mouse model has clinical significance, we examined the expression of IL‐17RB in human breast cancer specimens, including primary tumors and LN metastasis from the same patients by immunohistochemistry (IHC)." (PMID 28993429, 2017). "Previously, it was shown that a simple homeobox B13:interleukin 17 receptor B two-gene ratio (hereafter referred to as HOXB13:IL17BR) could predict recurrence in a sample of patients with estrogen receptor (ER)-positive breast cancer receiving adjuvant tamoxifen therapy." (PMID 23497539, 2013). "Investigations into the underlying mechanisms revealed that CHDH influences the expression of IL17RB and activates Cyclic‐AMP Response Element‐Binding Protein (CREB), thereby mediating breast cancer metastasis." (PMID 40928004, 2025). "The application of an IL17RB antibody and the CREB inhibitor 666‐15 effectively abolished CHDH‐mediated migration of breast cancer cells in vitro." (PMID 40928004, 2025). "Genes extracted from the gene expression omic dataset that play key roles in the development of breast cancer are CDCA5, IL17RB, MUC2, NOD2, and NXPH4." (PMID 35205681, 2022). "Amplified signaling of IL17RB and related ligand IL17B enhanced tumorigenicity in breast cancer cells and activated NF-κB to upregulate anti-apoptotic factor Bcl-2 and induced etoposide resistance." (PMID 34724890, 2021). "In this regard, they have shown that IL‐25 and IL‐17RB interaction phosphorylates c‐Raf, ERK, and p70S6 kinases in breast cancer cells (MCF‐7, IJG‐1731, and T47D cells lines)." (PMID 34128588, 2021). "Further investigation affirmed that the initiation of IL‐17RB/IL‐17B signaling is crucial for breast tumorigenesis which its expression is correlated with HER2 amplification and poor prognosis in breast cancer patients." (PMID 34128588, 2021). "TGF-β secreted by Treg cells up-regulates IL-17RB on 4T1 and EMT6 murine breast cancer cells via Smad2/3/4 signaling and increases their tumor growth and metastatic potential in vivo." (PMID 32373132, 2020). "Aberrant downstream effects of IL17RB include promotion of ERK-signalling in thyroid cancer cells, and activation of NFkB or STAT3 in breast cancer cells." (PMID 30680064, 2018). "In breast cancer, IL-17RB engagement by IL-17B triggers TRAF6 recruitment to IL-17RB, NF-κB activation and induction of the bcl-2 gene to inhibit apoptosis." (PMID 25340344, 2014). "During the treatments with veliparib and ponatinib, SNVs occurred on or near LATS1 (a core component of Hippo-YAP pathway), MGMT (related to DNA damage), IL17RB (related to NF-κB signaling) and APCDD1L (related to wnt signaling), all of which are known to be related to breast cancer." (PMID 29208983, 2017).
breast cancer (continued). "Pre-treatment with rIL-17B significantly decreased paclitaxel-induced cytotoxicity in BT20 and MDA-MB-468 cells (derived from TN/basal-like breast cancers) and also in MCF7 cells (from a luminal A breast cancer), while it had not effect on the IL-17RB negative MDA-MB-435S cell line." (PMID 29371916, 2017). "To address this question, we assessed the expression of IL-17E, IL-17RA, IL-17RC and IL-17RB in various human breast cancer cell lines as well as in non-transformed mammary epithelial cells MCF10A, in primary tumor cells (IJG-1731) derived ex vivo from an ER-negative breast cancer biopsy." (PMID 26154409, 2015). "Although IL-17E did not induce apoptosis of IL-17RB expressing breast cancer cells, we tested whether it could modulate cell death induced by chemotherapy drugs." (PMID 26154409, 2015). "In line with the results obtained from biopsies, IL-17RB was undetectable in non-transformed MCF10A cells and significantly upregulated in most breast cancer cell lines tested; suggesting that increased expression of IL17RB could be a malignant trait." (PMID 26154409, 2015).
asthma (17 papers, 2011 to 2025). "Further, there is evidence of an intronic IL17RB variant (+5561G>A) in which the minor allele is protective against asthma and associated with lower IL17RB expression." (PMID 36685501, 2022). "Previous studies identified an association between asthma susceptibility and a variant in IL17RB as well as IL33 which was also associated across diverse ancestries." (PMID 36685501, 2022). "A previous study reported that Il-17rb deficient mice were protected from asthma aggravation deriving from RSV infection, establishing that the IL-17 family plays an important role in the pathogenesis of RSV-induced asthma." (PMID 36119076, 2022). "Seven hypermethylated (CCL11, TNF, IL5, CCL2, CXCL1, CCL8, IL17RB) mRNAs (>twofold compared with control) were finally selected, as their mRNAs have been clearly reported as being associated with asthma." (PMID 36250525, 2022). "The transcriptional profile of human CRTH2+ CD4+ T cells was studied in the context of asthma, where it was found that IL17RB, which encodes for the IL-25R, had a ~3.35-fold increase in transcripts in asthma patients compared to healthy controls." (PMID 33374787, 2020). "Moreover, a rare polymorphism in IL-17RB, the signaling receptor for IL-25, is associated with a reduced incidence of asthma." (PMID 39717777, 2024). "Taken together, these observations suggest that genetic variations that increase IL17RB expression may increase the risk for asthma, particularly in those exposed to respiratory infections." (PMID 36685501, 2022). "Polymorphisms in the IL-17RB gene in humans have been linked with asthma susceptibility." (PMID 29456832, 2018). "Of note, exploratory analyses of the relationship between IL17RB transcript abundance and other intermediate asthma phenotypes revealed evidence of association with both total serum eosinophil count (p value = 6 × 10-6) and methacholine PC20 (p value = 4 × 10-4)." (PMID 21473777, 2011). "In our previous study, we showed that the IL-25 receptor, IL-17RB, can be expressed by CFs of patients with asthma." (PMID 37635231, 2023). "Accumulating evidence shows that ITGB4, SEMA3D, FCAR (Fc fragment of IgA receptor), KIT (KIT proto-oncogene, receptor tyrosine kinase), PGLYRP1, IL17RB, BIRC5 and PTGS1 are associated with prognosis in asthma." (PMID 36837510, 2023). "The percentages of total and IL-17RB+CFs in patients with asthma were significantly higher in the FAL group compared with those without FAL." (PMID 37635231, 2023). "IL-17RB activation can regulate gene expression responsible for the inflammatory and remodeling in asthma by the JNK, MAPK, NF-κB pathways." (PMID 36250525, 2022). "Here we used human endobronchial biopsies and differentiated primary human BECs (healthy donors and patients with asthma) to gain insight into coexpression of IL-25 and IL-17RB by differentiated BECs." (PMID 35508632, 2022). "It is worth noticing that IL-17RA together with IL-17RB is an important part of IL-25 signaling—an epithelial derived alarmin significant in asthma pathobiology." (PMID 32842623, 2020). "In summary, IL-25 high affinity receptor part (IL-17RB) expression on EoP is increased in the peripheral blood of subjects with asthma after allergen challenge." (PMID 29456832, 2018). "First, we suggest that IL-25- and IL-17RB+-CFs may serve as specific disease markers in patients with asthma and FAL." (PMID 37635231, 2023). "In a previous study, plasma IL-25 concentrations, IL25 mRNA levels in bronchial brushings, and the expression of the IL-25 receptors IL-17RA and IL-17RB on eosinophils in subjects with severe asthma were observed to be significantly higher than those in normal subjects." (PMID 36674744, 2023). "In addition, we believe that the IL-25-(IL-17RB +)-CFs axis is not only a disease biomarker for asthma with FAL but also an important contributor to airway fibrosis and remodeling." (PMID 37635231, 2023).